BMP4 (bone morphogenetic protein 4)
Diseases named in the same sentence as BMP4 in open-access papers (continued):
Sharing a sentence is not in itself a finding about the gene and the disease.
polycystic ovary syndrome (4 papers, 2015 to 2024). A disorder that manifests as multiple cysts on the ovaries. "BMP4 and its receptor are widely expressed in the ovary, and dysregulation of BMP4 expression may play an important role in follicular development and polycystic ovary syndrome (PCOS), which has a strong association with ovarian fibrosis." (PMID 38970048, 2024). "Adipocyte-specific overexpression of Bmp4 in mice protects against hyperandrogenemia and polycystic ovary syndrome." (PMID 39872218, 2024). "Previous studies have shown that several BMPs, including BMP2, BMP4, BMP5, BMP6, BMP7 and BMP8A are expressed in the granulosa cells from normally cycling and polycystic ovary syndrome women." (PMID 35395768, 2022).
preeclampsia (4 papers, 2020 to 2025). Preeclampsia is a hypertensive disorder of pregnancy that is characterized by new-onset hypertension with proteinuria presenting after 20 weeks of gestation, and depending on mild or severe forms may initially present with severe headache, visual disturbances, and hyperreflexia. "The potential involvement of BMP-4 and inflammatory mediators and crosstalk in context of other factors involved in preterm preeclampsia are depicted in the sketch diagram." (PMID 34195300, 2021). "We herein provide an independent evaluation and confirm the increased levels of BMP-4 in the sera of preterm preeclampsia patients." (PMID 34195300, 2021). "A mouse model of preeclampsia with high sEng plasma levels (sEng+) showed increased transcript levels of BMP4 in lungs, stomach, and duodenum, and increased circulating levels of BMP4, compared to those of control animals." (PMID 32316263, 2020). "The resulting WT pregnant female bearing sEng+ fetuses [fWT(sEng+)] constitutes a useful model of preeclampsia, where the kinetic changes in sEng and BMP4 plasma levels as well as in SBP, all of them related to placental development, can be monitored." (PMID 32316263, 2020). "Because abnormal levels of sEng are found not only in preeclampsia, but also in several vascular- and inflammation-related pathological conditions, these results suggest that BMP4 may be a sEng-induced mediator, regulating endothelial function in these pathologies." (PMID 32316263, 2020). "In agreement with the sEng-dependent upregulation of BMP4 observed in vitro, we found a positive correlation between the levels of both proteins in the sera of pregnant women with or without preeclampsia, a disease where sEng levels are abnormally elevated." (PMID 32316263, 2020). "Furthermore, a positive correlation between sEng and BMP4 levels in circulation was observed in pregnant women, regardless of preeclampsia status." (PMID 41039222, 2025). "Also, serum levels of sEng and BMP4 were positively correlated in pregnant women with and without preeclampsia." (PMID 32316263, 2020).
renal agenesis (4 papers, 2011 to 2021). Renal agenesis (RA) is a form of renal tract malformation characterized by the complete absence of development of one or both kidneys (unilateral RA or bilateral RA respectively), accompanied by absent ureter(s). "This proposal is in line with the spectrum of renal abnormalities seen in GDF6 variant carriers that includes renal agenesis and renal hypodysplasia (two cases here), two anomalies also found in patients carrying BMP4 variants." (PMID 32737436, 2020). "On the other hand, mutations in RDGs such as Six2 and Bmp4 are identified only in 3% of children from European population with nonsyndromic CAKUT that include unilateral renal agenesis and renal hypodysplasia." (PMID 22685656, 2012). "The bilateral renal agenesis in Grem1-deficient mice is restored by additional inactivation of one Bmp4 allele." (PMID 21552539, 2011). "Genetic analysis in the mouse revealed that GREMLIN1 (GREM1)-mediated antagonism of BMP4 is essential for ureteric epithelial branching as the disruption of ureteric bud outgrowth and renal agenesis in Grem1-deficient embryos is restored by additional inactivation of one Bmp4 allele." (PMID 21552539, 2011). "The timely reduction in Bmp4 by its modifier Gremlin1 in the mesenchyme surrounding each nephric duct is required for Gdnf/c-Ret dependent branching morphogenesis; failure to suppress Bmp4 leads to renal agenesis." (PMID 35076510, 2021). "Massively parallel exon sequencing of 30 candidate genes in pooled DNA from children with unilateral renal agenesis, renal hypodysplasia, or VUR in the United States identified novel mutations in 4 genes (Ret, BMP4, FRAS1, and FREM2) in 17% of cases." (PMID 22685656, 2012).
renal carcinoma (4 papers, 2010 to 2017). A carcinoma arising from the epithelium of the renal parenchyma or the renal pelvis. "For example, MDM2, SLC16A3, LFT etc. show expression change in renal cancer; SLC22A7, ACHE, BMP4 etc. are associated with renal function." (PMID 27258182, 2016). "Out of the unique set of genes detected by BNNPT, a few were reported to be relevant to renal cancer or disease: CDCP1, GSTT1, E2F3, MAPK1, SALL4, SIRT1, ADAMTS13, Gfrα1, ASPH, MIR17HG, APOE, BMP4, RCOR1, NUMB and SEC63." (PMID 28986523, 2017).
renal dysplasia (4 papers, 2012 to 2024). Renal dysplasia is a form of renal malformation in which the kidney(s) are present but their development is abnormal and incomplete. "We investigate a variant in the gene encoding growth factor BMP4 in a family with Stickler syndrome with associated renal dysplasia." (PMID 30568244, 2019). "This is exemplified by a family with Stickler syndrome and a heterozygous nonsense variant in the BMP4 gene encoding bone morphogenetic protein 4, a ligand related to GDF6, with renal dysplasia in only one of five family members carrying the BMP4 variant." (PMID 32737436, 2020).
rheumatoid arthritis (4 papers, 2020 to 2025). A chronic, systemic autoimmune disorder characterized by inflammation in the synovial membranes and articular surfaces. "However, a decrease in BMP-4 expression has already been observed in synovial tissue of patients with OA and rheumatoid arthritis." (PMID 33046134, 2020). "It is a member of the ‘role of osteoclasts in rheumatoid arthritis signalling’ CP, which was strongly activated in both DMD and BMP4‐stimulated transcriptomes." (PMID 40641092, 2025). "In patients with rheumatoid arthritis, stimulation with IL-1β induced BMP-2 and BMP-6, but not BMP-4, BMP-5, or BMP-7 in fibroblast-like synoviocytes." (PMID 32290085, 2020).
Stickler syndrome (4 papers, 2019 to 2022). Stickler syndrome is an inherited vitreoretinopathy characterized by the association of ocular signs with more or less complete forms of Pierre-Robin sequence, bone disorders, and sensorineural deafness (10% of cases). "The BMP4 phenotype is associated with variable ocular manifestations, ranging from anophthalmia to stigmata associated with Stickler syndrome such as high myopia, retinal detachment and a congenital vitreous anomaly." (PMID 36140739, 2022). "This is the first report of a BMP4 DNA variant causing Stickler syndrome, and we suggest BMP4 be added to standard diagnostic gene panels for this condition." (PMID 30568244, 2019). "If a loss-of-function BMP4 variant is identified in a patient with Stickler syndrome then patients should be investigated for CAKUT, and conversely if identified in a patient with CAKUT, they should be referred for ophthalmological assessment." (PMID 30568244, 2019). "Next generation sequencing identified a sequence variant in the gene for BMP4, which segregated with the Stickler syndrome phenotype in this family." (PMID 30568244, 2019). "We have described a novel variant in a gene, BMP4, associated with a Stickler syndrome phenotype." (PMID 30568244, 2019). "As pathogenic variants in this region of COL2A1 can result in type 1 Stickler syndrome, it has been suggested that haploinsufficiency of BMP4 may affect these interactions with type II collagen, disrupting the development of vitreous and cartilage, producing a similar phenotype." (PMID 35741851, 2022). "The p.(Gly44Ter) pathogenic variant in the BMP4 gene was linked to Stickler syndrome phenotype in one case report, and it is the only non-collagenous form of AD Stickler syndrome reported." (PMID 35741851, 2022). "Retrognathia and a high-arched palate were also seen in this family, as well as renal dysplasia, the latter being typical for BMP4 mutations but not for Stickler syndrome." (PMID 36140739, 2022).
age-related macular degeneration (3 papers, 2009 to 2021). Age-related loss of vision in the central portion of the retina (macula), secondary to retinal degeneration. "Remarkably, human ocular samples from neovascular age-related macular degeneration (AMD) donors were rich in BMP2 and BMP4, particularly in RPE and choroid rather than in retina." (PMID 33919531, 2021).
basal cell carcinoma (3 papers, 2014 to 2023). A carcinoma involving the basal cells. "The regulatory network also showed that DEGs including LEF1, FZD3, SMAD3, and BMP4 were important regulators of the Wnt signaling, basal cell carcinoma, and Hippo signaling pathways." (PMID 36979137, 2023). "BMP4 was enriched in KEGG pathways associated with pathways in cancer and basal cell carcinoma in this study." (PMID 28947976, 2017). "BMP4 was involved in the pathways of cancer, basal cell carcinoma, hedgehog signaling, TGF-beta signaling and cytokine-cytokine receptor interaction." (PMID 25198128, 2014).
bladder tumors (3 papers, 2019 to 2024). "We found that, compared with wild-type bladder tumor organoids, Bmp4-expressing tumor organoids showed growth reductions after transplantation." (PMID 31036156, 2019). "However, these cells have functional plasticity and can evolve into tissue repair anti-inflammatory M2 macrophages, induced by M2 polarizing cytokines (CCL2, IL-10, and TGF-β) and bone morphogenetic protein 4 (BMP-4) produced by bladder tumors." (PMID 39682686, 2024).
cervical cancer (3 papers, 2024 to 2025). A primary or metastatic malignant neoplasm involving the cervix. "Remarkably, FTO upregulates the expression of BMP4 in an m6A-dependent manner and binds to the N-terminal of BMP4 to form a dimer at the C-terminal in cervical cancer cells through protein–protein interaction." (PMID 40429638, 2025). "FTO’s influence on BMP4 regulation indicates a profound indirect contribution to the progression of cervical cancer, observable in both controlled laboratory settings and clinical scenarios." (PMID 39175477, 2024). "has demonstrated that BMP4 treatments not only encourage the growth of cervical cancer cells in vitro but also effectively inhibit the Hippo/YAP1/TAZ signaling pathway by reducing FTO levels." (PMID 39175477, 2024).
Cirrhosis (3 papers, 2013 to 2022). A chronic disorder of the liver in which liver tissue becomes scarred and is partially replaced by regenerative nodules and fibrotic tissue resulting in loss of liver function. "The percentage of BMP4-positive cells was significantly increased in endothelial and mesenchymal cells (Padj < 0.05) in cirrhosis and to some extent in hepatocytes or cholangiocytes." (PMID 35995996, 2022). "Protein expression of BMP-4 and BMP-7 was upregulated in HBV-related human cirrhosis/HCC samples, and the overexpression of BMP-4 and BMP-7 increased cell viability and enhanced cell migration in HCC cell-lines." (PMID 32050622, 2020).
congenital heart disease (3 papers, 2014 to 2023). A heart disease that is present at birth. "Our study is the first according to our knowledge that examined all exons of the BMP2 and BMP4 genes to determine possible molecular defects such as insertions/deletions or single nucleotide polymorphisms (SNPs) that are possibly associated with the risk of congenital heart disease." (PMID 37627976, 2023). "Under the clinical settings that GC application is inevitable, the addition of exogenous BMP4 may provide a promising treatment for the congenital heart diseases." (PMID 30082698, 2018). "To provide some insight into the role of BMP-2 and -4 in ASD, VSD and other complex congenital defects, in the present study we examined 52 cases of congenital heart defects (ASD, VSD and complex defects) for possible molecular defects in the BMP2 and BMP4 genes." (PMID 37627976, 2023). "Moreover, when each of the congenital heart defect subgroups (ASD, VSD, Fallot, Complex/other) was compared with the normal hearts, similar BMP4 protein expression levels were found (p = 0.48, p = 0.31, p = 0.68, p = 0.64 respectively, t-test)." (PMID 37627976, 2023). "Sanger sequencing of all coding exons of BMP2 and BMP4 genes was performed on all 52 patients with a congenital heart disease, as well as on 100 blood donors with non-CHD hearts." (PMID 37627976, 2023). "Moreover, when each of the congenital heart defect subgroups ASD and VSD was compared to the normal hearts, similar fold expression values were found regarding BMP2 mRNA (p = 0.72, p = 0.33, respectively, t-test) and BMP4 mRNA (p = 1.00, p = 0.99, respectively, t-test)." (PMID 37627976, 2023).
coronary artery disease (3 papers, 2017 to 2022). "In humans, higher expression of BMP4 was also found in the hearts of patients with coronary artery disease and dilated cardiomyopathy." (PMID 32319199, 2020). "In ischemic heart disease, FSTL1 prevents myocytes apoptosis through inhibiting BMP4-p-Smad1/5/8 signaling and enhancing AMPK pathway." (PMID 28852126, 2017).
Duchenne muscular dystrophy (3 papers, 2020 to 2025). Duchenne muscular dystrophy (DMD) is a neuromuscular disease characterized by rapidly progressive muscle weakness and wasting due to degeneration of skeletal, smooth and cardiac muscle. "In Duchenne muscular dystrophy, the BMP4/SMAD8 pathway is upregulated alongside IL-6, a key inflammatory mediator." (PMID 40076910, 2025). "In Duchenne muscular dystrophy (DMD), one of the most prevalent myopathies, Bmp4 was shown to be higher than in control samples and this increase was associated with the defective differentiation of myoblasts into myotubes." (PMID 32053985, 2020).
hyperlipidemia (3 papers, 2021 to 2024). "Building upon these benchmark data, we sought to explore the impact of prolonged hyperlipidemia as well as the effect colchicine-based therapy on a variety of atheroprotective (Klotho, HOXA5, NOTCH1, and OCT4) and proatherogenic (HIF1a, SOX2, BMP4, and NANOG) genes." (PMID 36362692, 2022).
invasive breast carcinoma (3 papers, 2015 to 2019). A carcinoma that infiltrates the breast parenchyma. "Similarly to BMP7, expression of BMP4 is low in invasive breast cancer and its signalling has been implicated in the maintenance of tumor dormancy." (PMID 27409832, 2016).
lung diseases (3 papers, 2020 to 2022). "However, the role of BMP4 in lung diseases and the regulatory effect of FGF10 on BMP4 are not fully understood." (PMID 36618911, 2022).
medulloblastoma (3 papers, 2015 to 2022). A malignant, invasive embryonal neoplasm arising from the cerebellum. "A recent paper showed that the BMP4 signaling pathway promotes trans-differentiation of tumor cells in relapsed medulloblastoma, supporting the argument that this pathway could acts in maintaining the CSC pool in both primary and relapsed tumors." (PMID 35565225, 2022). "BMP4 can inhibit medulloblastoma proliferation and induce differentiation of medulloblastoma cells." (PMID 32508873, 2020). "Additionally, these modules were interconnected via several hub genes, namely, FGFR1, BMP4, PAX6, PAX3, SOX9, and GLI2, all of which have been related to medulloblastomas in previous studies." (PMID 32508873, 2020).
meningioma (3 papers, 2007 to 2024). A generally slow growing tumor attached to the dura mater. "BMP4 stimulates meningioma cell proliferation and phosphorylation/activation of Smad1 playing autocrine/paracrine roles and interacting with other transforming growth factor-beta superfamily members in regulating meningioma growth and differentiation." (PMID 32244473, 2020). "In line with the microarray data, the PCR data showed a decrease in the median expression level of BMP4, SMAD9, JUN, RUNX2 and an increase in the median expression level of FKBP1A in Grade 3 meningiomas when compared to Grade 1 meningiomas." (PMID 17937814, 2007).
metastatic cancer (3 papers, 2019 to 2024). A carcinoma which has spread from the original site of growth to another anatomic site. "The results showed that BMP4 was highly expressed in primary cancers that developed bone-only metastasis and metastatic cancers in bone, compared with primary cancers that developed other distant organ metastasis and metastatic cancers in other organs, respectively." (PMID 31222004, 2019). "We also noted that high BMP4 exerted a selective suppressive effect on metastatic disease without impacting behaviour of the primary tumour, suggesting that the anti-metastatic pathways governed by BMP4 might have substantial relevance to metastatic cancer control in the clinic." (PMID 39273106, 2024). "Interestingly, several well-known oncogenes linked to aggressive and metastatic cancer phenotype, including CXCL1, CXCL2, MYC, and BMP4, were included in this gene get, suggesting that BRD4 and STAT3 can coordinately regulate the oncogenic enhancer activity to promote tumor progression." (PMID 34290255, 2021).
Oligodontia (3 papers, 2020 to 2023). The absence of six or more teeth from the normal series by a failure to develop. "MSX1 gene mutations can lead to hypodontia or oligodontia as well as variations in the downstream signaling gene bone morphogenetic protein 4 (BMP4)." (PMID 33693441, 2020). "Previous studies have reported that variants of BMP4 are related to oligodontia in humans." (PMID 36675162, 2023).
Osteochondroma (3 papers, 2015 to 2021). A common, benign cartiliginous neoplasm arising from the metaphysis of bone. "Pathological diagnosis was osteochondroma; immunohistochemistry showed that the tumor exhibited a conspicuous expression of BMP-4 and BMP-2 but rarely expression of PCNA." (PMID 25664314, 2015). "IHC staining for osteogenetic protein expression in the BPOP specimen was conspicuously positive for both BMP-2 and BMP-4, which are known to indicate osteogenesis and chondrogenesis, respectively, while osteochondroma was much more weakly positive for these proteins." (PMID 26865041, 2016). "Thus, the enhanced BMP4/6-sensitivity and GAG-production discovered here for Ext1gt/gt rib chondrocytes is in line with findings on pharmacological or structural HS-depletion in mesenchymal progenitors and on HS-deficient osteochondroma cells in animal models of HME." (PMID 33918436, 2021). "BMP-2 and BMP-4, which are markers of osteogenesis and chondrogenesis, respectively, were consistently positive in BPOP but only weakly positive in osteochondroma." (PMID 26865041, 2016).
Peri-Implantitis (3 papers, 2024 to 2025). An inflammatory process with loss of supporting bone in the tissues surrounding functioning DENTAL IMPLANTS. "The mutations of OPG, BMP-4 and FGF-3 in patients with PI who are heavy smokers or diabetics could explain why these two conditions are risk factors for peri-implantitis." (PMID 38840172, 2024). "The aim was to evaluate the association between single-nucleotide polymorphisms (SNPs) in genes involved in inflammation and bone metabolism (BMP-4, BRINP3, CD14, FGF-3, FGF-10, GBP-1, IL-1α, IL-1β, IL-10, LTF, OPG, and RANKL) and peri-implantitis." (PMID 41373620, 2025).